TPO (thyroid peroxidase)
Diseases named in the same sentence as TPO in open-access papers (continued):
Sharing a sentence is not in itself a finding about the gene and the disease.
vitamin D deficiency (22 papers, 2015 to 2025). A nutritional condition produced by a deficiency of VITAMIN D in the diet, insufficient production of vitamin D in the skin, inadequate absorption of vitamin D from the diet, or abnormal conversion of vitamin D to its bioactive metabolites. "In the presence of vitamin D deficiency there was a 3.107 fold increase in HT (%95 CI: 1.530–6.307, p= 0.001), and 2.604 fold increase in anti-TPO positivity (%95 CI: 1.280–5.291, p= 0.004)." (PMID 40837651, 2025). "This study confirms an inverse correlation between vitamin D deficiency and chronic autoimmune thyroiditis, as indicated by elevated anti-TPO levels in patients with lower 25(OH)D concentrations." (PMID 40458336, 2025). "In the univariate analysis, anti-Tg (OR = 0.626; 95% CI: 0.489–0.801; P < .001) and anti-TPO positivity (OR = 0.662; 95% CI: 0.518–0.846; P = .001) were significantly associated with a lower likelihood of vitamin D deficiency." (PMID 41261692, 2025). "The risk analysis in our study showed that in vitamin D deficiency, the presence of HT increased by 3.107 fold (OR: 3.107, %95 CI: 1.530-6.307, p= 0.001), and anti-TPO positivity increased by 2.604 fold (OR: 2.604, %95 CI: 1.280-5.291, p= 0.004)." (PMID 40837651, 2025). "We found the presence of anti-thyroid peroxidase antibodies (Hashimoto’s thyroiditis) and vitamin D deficiency." (PMID 40710038, 2025). "The levels of anti-TPO, anti-TG and the number of patients positive for anti-TPO were significantly higher in the groups with vitamin D deficiency or insufficiency, compared to the group with sufficient vitamin D (p<0.001, p=0.026, p=0.006, respectively)." (PMID 40837651, 2025). "Thyroid function was normal with normal levels of thyroid peroxidase and thyroglobulin antibodies while vitamin D deficiency was found." (PMID 40710038, 2025). "We collected data of 1263 patients about anti-TPO and vitamin D. According to them, 71.2% had vitamin D deficiency, 23.7% had vitamin D insufficiency, and only 5.1% had normal vitamin D levels." (PMID 34457000, 2021). "Following oral Vitamin D3 supplementation given to patients with vitamin D deficiency for a while, a significant decrease was detected in the control anti-TPO levels." (PMID 35317375, 2021). "Patients with vitamin D deficiency/insufficiency have generally been studied in correlation with serum anti-TPO thyroid antibodies levels." (PMID 30356853, 2018). "The present findings show that more of the participants with vitamin D deficiency had anti-TPO positivity and lower TSH levels, as compared to those with a normal vitamin D level." (PMID 25654127, 2015). "For instance, one study highlighted that lower vitamin D levels were associated with elevated anti-TPO antibody titers, suggesting that vitamin D deficiency may exacerbate autoimmune responses in HT patients." (PMID 40822954, 2025). "In this study, a marked deficiency of 25(OH)D was observed in patients with elevated anti-TPO levels compared to those with adequate vitamin D, reinforcing the potential role of vitamin D deficiency as a contributing factor in the pathogenesis and severity of chronic autoimmune thyroiditis." (PMID 40458336, 2025). "Vitamin D deficiency was higher in patients with elevated anti-TPO (74.9% vs. 69.7%)." (PMID 34457000, 2021). "TPO Ab and TgAb levels were found higher in patients with vitamin D insufficiency/deficiency." (PMID 28523025, 2017). "The objective of the present study was to investigates the effect of vitamin D deficiency on the changes in the levels of TSH, TPO-Ab, IL-1 and hsCRP in pregnant women with subclinical hypothyroidism (hereinafter referred to as SCH) in the first trimester." (PMID 32968400, 2020). "Individuals with negative anti-TPO and anti-Tg antibodies had a higher risk of vitamin D deficiency, a somewhat unexpected result." (PMID 41261692, 2025).
vitamin D deficiency (continued). "Interestingly, women with vitamin D deficiency presented lower FT3 and FT4 and higher TSH and anti-TG and anti-TPO positivity than men (all p < 0.001)." (PMID 37686729, 2023). "Anti-TPO levels were also significantly higher in vitamin D-deficient HT patients (25(OH)D level < 75 nmol/L) compared to HT patients with no vitamin D deficiency." (PMID 28895880, 2017). "Patients with AT and vitamin D deficiency had a comparable hormonal profile compared to patients with AT and vitamin D sufficiency in terms of TSH (p = 0.39), FT3 (p = 0.30), FT4 (p = 0.31), TG-Ab (0.44) and TPO-Ab (0.35)." (PMID 27571093, 2016). "Vitamin D supplementation was shown to lower mean TSH levels and anti-TPO levels, and vitamin D deficiency may be beneficial as a negative prognostic indicator." (PMID 35165540, 2022).
COVID-19 (20 papers, 2021 to 2025). A disease caused by infection with severe acute respiratory syndrome coronavirus 2. "They drew attention to a possible further increased risk of thrombosis in patients with COVID-19 from ITP or its treatment (particularly with TPO-RA)." (PMID 33669423, 2021). "IFN for COVID-19 was associated with modest increases in anti-thyroid antibody titres, and a trend of more incident anti-TPO positivity and abnormal TFTs during convalescence." (PMID 34659128, 2021). "Higher anti-TPO levels accompanied by lower fT3 and fT4 levels were reported in severe patients, indicating that COVID-19 and the associated cytokine storm may disrupt the HPT axis." (PMID 40735669, 2024). "Several case reports have shown that, in some individuals, the anti-TPO titer increases during COVID-19 and the post-recovery period." (PMID 39450181, 2024). "Many SAT cases in COVID-19 patients reported elevated thyroid autoantibodies (anti-TPO, anti-Tg, and TRAb), which is uncommon in classic SAT." (PMID 39544551, 2024). "Previous longitudinal studies have reported preexisting but not new-onset autoantibodies to the clinically important autoantigen TPO in COVID-19 patients." (PMID 39414823, 2024). "In contrast, we found new-onset anti-TPO IgG in 4% (n = 22) of the longitudinal cohort, with a higher prevalence in hospitalized COVID-19 patients than in HCW with mild to moderate disease." (PMID 39414823, 2024). "In other studies, the fT4 levels were not significantly changed Some studies also found increased levels of anti-thyroid peroxidase (anti-TPO) and anti-thyroglobulin (anti-Tg) antibodies in COVID-19 patients." (PMID 40735669, 2024). "With the high anti-TPO concentration, this likely represented preexisting Hashimoto thyroiditis diagnosed during hospitalization for COVID-19." (PMID 36831150, 2023). "Updated treatment guidelines will therefore be required if adequate new studies of TPO-RAs in the first-line setting or in specific patient groups such as COVID-19 ITP patients become available." (PMID 36826482, 2023). "Subgroup analysis revealed that symptom recovery occurred more among patients with positive anti-TPO at the time of re-evaluation, suggesting a potential protective role of anti-TPO in post-COVID-19 condition." (PMID 35455008, 2022). "Thyroid autoimmunity, evaluated through the presence of anti-TPO antibodies, was common in COVID-19 patients as compared with pre-pandemic controls." (PMID 35455008, 2022). "There are recommendations for preventing these complications; for example, TPO-RA should be avoided in patients with acute ITP and COVID-19 due to the higher risk of thrombosis and hepatotoxicity." (PMID 33804346, 2021). "Our main finding was that interferon beta-1b treatment for COVID-19, even for such a short duration of a few days, could induce modest increases in anti-thyroid antibody titres and be associated with more incident anti-TPO positivity upon reassessment at three months." (PMID 34659128, 2021). "Therefore, the current study aimed to assess the menstrual disorder and the AMH, TSH, TPO, and prolactin levels in female patients with COVID-19." (PMID 39906086, 2024). "Additionally, we compared the levels of autoantibodies previously identified during acute or critical COVID-19, including anti-dsDNA, anti-cardiolipin, anti-β2-glycoprotein I, anti-neutrophil cytoplasmic antibodies, and anti-thyroid peroxidase (anti-TPO)." (PMID 39450181, 2024). "However, we note that only one of the five epitope-mapped autoantibodies, anti-TPO IgG, have been previously reported in proteome-scale autoantibody studies of COVID-19, with a reported prevalence ranging from 012,16,27,43,54 to 2%15." (PMID 39414823, 2024). "Furthermore, we determined the levels of several AABs previously identified in acute or critical COVID-19 cases, including anti-dsDNA, anti-cardiolipin, anti-β2-glycoprotein I, anti-neutrophil cytoplasmic antibodies, and anti-TPO." (PMID 39450181, 2024).
COVID-19 (continued). "CSF examination revealed five cases with abnormalities: anti-thyroid antibodies (anti-TG, TRAK, anti-TPO, and anti-TRAb) (#16&#77), COVID-19 (#111), neurosyphilis (#30), and twice OCBs type II and typical white matter lesions on brain MRI, that were diagnosed as multiple sclerosis (#49&51)." (PMID 33785807, 2021). "Among the categorical variables, only interferon beta-1b treatment was significantly associated with changes in anti-TPO titres (p=0.001), but not sex, smoking/drinking, abnormal TFTs on admission, baseline COVID-19 severity, baseline anti-TPO positivity, baseline lymphopenia or comorbidities." (PMID 34659128, 2021). "In addition to the seven consensus statements, the experts also considered and discussed TPO-RA treatment in two further patient populations but failed to reach a consensus: chronic ITP patients with mild/moderate COVID-19 and treatment of ITP patients in the first-line setting." (PMID 36826482, 2023). "Another study, conducted in Hong Kong on 191 hospitalized COVID-19 patients, showed low TSH in 13.1% and high TSH and TPO antibody titer in only one patient." (PMID 39544551, 2024). "A recent study enrolled 2765 patients and revealed that a COVID-19 vaccination seemed to induce increased levels of TSH followed by mood disturbance, and pre-vaccine serum TSH, CRP, and anti-TPO should be evaluated." (PMID 38137646, 2023). "An earlier systematic review by Bhattacharjee and Banerjee reported that no adverse effects were observed with a short duration of TPO-RA as second-line therapy in a few COVID-19 cases (n = 9)." (PMID 36826482, 2023). "Unsurprisingly, the experts in this study did not concur on the possibility of switching to another TPO-RA for chronic ITP patients in case of relapse already on TPO-RA therapy with newly identified mild/moderate COVID-19." (PMID 36826482, 2023). "Last but not least, a recent study of 72 healthy individuals in Greece showed no clinically significant change in thyroid function, anti-thyroid peroxidase and anti-thyroglobulin antibody titres up to one month after the second dose of mRNA COVID-19 vaccines." (PMID 36229814, 2022). "In a comprehensive review of reported cases in the literature, Berger and Rodgers (2021) concluded that treatment regimens including TPO-RAs are most effective for obtaining a complete response, and steroids may be more effective than IVIG in patients with ITP secondary to COVID-19." (PMID 36826482, 2023). "In addition, the expert panel discussed TPO-RA treatment in chronic ITP patients with mild/moderate COVID-19 and ITP patients in the first-line setting but failed to reach consensus." (PMID 36826482, 2023). "None of the 24 patients diagnosed with ITP with suggestive COVID-19 developed thrombotic events during the infection despite the fact that four had been administered thrombopoietin receptor agonists (TPO-RA), six had been splenectomised, and seven had other prothrombotic risk factors." (PMID 33804346, 2021).
Hashimoto encephalopathy (20 papers, 2011 to 2025). "Hashimoto encephalopathy and autoimmune encephalitis can also cause a similar clinical picture, but thyroid peroxidase antibody and autoimmune encephalitis-related antibodies were negative in our patient." (PMID 31593101, 2019). "Hashimoto’s encephalopathy (HE) is a neurological condition associated with elevated anti-thyroid antibodies (anti-thyroglobulin or anti-thyroid peroxidase (TPO)), often occurring in euthyroid individuals." (PMID 29177818, 2017). "We reported a case of Hashimoto's encephalopathy with cerebellar ataxia as the main manifestation, elevated anti-thyroid antibodies (anti-TPO/TG), and normal thyroid function." (PMID 36081870, 2022). "Our study included 3 cases with Hashimotos encephalopathy with steroid responsiveness, though Anti-TPO antibody levels were found to be elevated in 8 cases." (PMID 29346380, 2018). "High titers of serum anti-TPO antibodies suggested comorbid diagnosis of Hashimoto encephalopathy (HE) requires further attentions." (PMID 22126669, 2011). "Hashimoto encephalopathy and autoimmune encephalitis also can cause a similar clinical picture but thyroid peroxidase antibody and NMDA receptor antibody were negative in our patient." (PMID 29058581, 2017). "Furthermore, no data on systemic inflammatory markers of thyroid- or tissue-specific autoantibodies (e.g., TPO or TGA) were available, limiting the assessment of alternative autoimmune encephalopathy syndromes such as Hashimoto’s encephalopathy." (PMID 40757033, 2025). "Hashimoto encephalopathy (HE) is a rare pathological condition with an estimated prevalence of 2/100,000 and various neuropsychiatric symptoms (NPS) combined with positive serum antithyroid-peroxidase autoantibodies (TPO-Abs, usually >200 U/mL)." (PMID 27688922, 2016).
thyroid dyshormonogenesis (19 papers, 2012 to 2025). "Typically, thyroid dyshormonogenesis is inherited in an autosomal recessive manner and mutations in the thyroid peroxidase (TPO) gene are the most common causes of inherited defects in CH." (PMID 40862110, 2025). "A comprehensive explanation has been illustrated disrupting interaction with H2O2 and iodide (I-) due to the effect of the nonsynonymous mutation on TPO dimer formation and its biological function for thyroid dyshormonogenesis." (PMID 37699049, 2023). "Genetic defective thyroid peroxidase (TPO) is considered as one of the most common causes of thyroid dyshormonogenesis." (PMID 35002963, 2021). "In patients with thyroid dyshormonogenesis, the detection rate of TPO mutations is 20–46% in Caucasians but only less than 10% in East Asians." (PMID 35002963, 2021). "Upon Sanger sequencing of specimens from the patients with thyroid dyshormonogenesis targeting exon-8 to exon-14 which are commonly reported in TPO-associated thyroid dyshormonogenesis, mutations were detected in all 36 samples." (PMID 30915365, 2019). "Because TPO gene mutation is the most frequent cause of thyroid dyshormonogenesis, the entire exons 1-17 and flanking regions of TPO gene were sequenced directly from genomic DNA." (PMID 26761947, 2016). "In this study, the prevalence of TPO gene mutations in patients with thyroid dyshormonogenesis in Isfahan was investigated." (PMID 22919382, 2012). "Of the several genetic defects responsible for thyroid dyshormonogenesis, mutations in thyroid peroxidase (TPO) gene are the most prevalent causes of inherited defects in CH." (PMID 22919382, 2012). "Seven causal genes for thyroid dyshormonogenesis were studied in these cases, including TPO." (PMID 39064575, 2024). "Thyroid dyshormonogenesis usually is caused by single gene mutations, encoding globulins involved in TH synthesis (thyroid peroxidase - TPO, thyroglobulin - TG, Na+/I- symporter – SCL5A5/NIS, pendrine – SCL26A4/PDS), or directly influencing TH synthesis and metabolism (DUOX2, DUOX2A, IYD/DEHAL1)." (PMID 35832434, 2022). "As mutations in the TPO gene are commonly associated with thyroid dyshormonogenesis and related complications, we opted to analyze the TPO gene to find whether there were mutations in this gene of the study participants." (PMID 30915365, 2019). "TPO gene mutations are the main causes of thyroid dyshormonogenesis." (PMID 22919382, 2012). "In conclusion, HRM-based molecular technique targeting variants c.1117G>T, c.1193G>C, and c.2173A>C could be used as a high throughput, rapid, reliable, and cost-effective screening approach for the detection of all common mutations in TPO gene in Bangladeshi patients with dyshormonogenesis." (PMID 38598477, 2024). "TPO (Thyroid Peroxidase) is known to be one of the major genes involved in congenital hypothyroid patients with thyroid dyshormonogenesis." (PMID 38598477, 2024). "In total, 92 of 132 (69.70%) mutations were related to thyroid dyshormonogenesis [DUOX2 (n = 49), TG (n = 35), and TPO (n = 8)]." (PMID 30420871, 2018). "It encodes thyroid peroxidase enzyme, which is a thyroid-specific glycosylated hemoprotein, and aberrant regulation of TPO can result in thyroid dyshormonogenesis." (PMID 28036280, 2017). "It is possible that mutations in intronic sequences or in the promoter region and unexamined regulatory regions of TPO gene are the cases of thyroid dyshormonogenesis in these patients." (PMID 22919382, 2012). "Considering the high prevalence of thyroid dyshormonogenesis in Isfahan and the role of TPO gene mutation in the etiology of this type of CH, in the present study, the frequency of TPO gene defects in patients with thyroid dyshormonogenesis was detected." (PMID 22919382, 2012). "In addition, 10%–15% of cases are caused by thyroid dyshormonogenesis, which is associated with mutations in thyroid DUOX2, DUOXA2, TG, and TPO." (PMID 37252044, 2023).
thyroid dyshormonogenesis (continued). "Although several genes have been reported to be involved in thyroid dyshormonogenesis (TDH), mutation in the TPO gene is frequently described with mild to severe repercussions resulting in partial iodine organification defect (PIOD) to total iodine organification defect (TIOD)." (PMID 30915365, 2019). "To determine the inheritance mode of CH caused by thyroid dyshormonogenesis, we analyzed 22 family trios, in which the probands carried compound heterozygous mutations in genes involved in thyroid hormone synthesis (DUOX2, DUOXA2, TPO and TG)." (PMID 29650690, 2018). "The most common defect in thyroid dyshormonogenesis resides in thyroid peroxidase (TPO) gene." (PMID 26761947, 2016).